SPHK1 (sphingosine kinase 1)
Diseases named in the same sentence as SPHK1 in open-access papers (continued):
Sharing a sentence is not in itself a finding about the gene and the disease.
tumor (continued). "Importantly, tumor growth and lung metastasis were suppressed when SPHK1 and NF-κB were therapeutically inhibited in the orthotopic syngeneic TNBC mouse model." (PMID 39063133, 2024). "Consequently, SphK1 inhibition was suggested as a possible strategy to control tumor hypoxia and its consequences." (PMID 36834678, 2023). "Thus, the SphK1/S1P/S1PR axis is involved both in autocrine signaling to promote tumor growth, as well as in paracrine signaling to augment angiogenesis." (PMID 36834678, 2023). "Indeed, several of these studies show that increased SPHK1 expression correlates with higher tumor grade and shorter patient survival." (PMID 36672428, 2023). "ACAT2 and SPHK1 were related to lipid metabolism and some tumor-promoting pathways, SNED1 might be related to cell matrix adhesion." (PMID 37202800, 2023). "Furthermore, SPHK1 was strongly correlated with patients’ prognosis and a malignant-tumor-behavior-related signature in PDAC patients." (PMID 37999228, 2023). "Many evidences show that activated SphK1 is involved in tumor genesis and resistance." (PMID 37305043, 2023). "Still, some previous reports indicate the tumor-promoting effects of high SPHK1 expression." (PMID 36823149, 2023). "Our in vivo data strongly suggest that targeting the SPHK1/S1P/S1PR axis might be a valuable approach in counteracting tumor development." (PMID 36672428, 2023). "Consequently, SPHK1‐packaged EVs elevate S1P levels in the tumor microenvironment, where S1P appears as an immunosuppressive agent." (PMID 35289120, 2022). "We also found that SPHK1‐packaged EVs produced similar effects, confirming our hypothesis that SPHK1‐EVs increase S1P levels in the tumor microenvironment." (PMID 35289120, 2022). "Finally, targeting SPHK1 or its downstream targets with clinically available inhibitors would be effective for tumor therapy, such as increasing tumor sensitivity to chemotherapy." (PMID 35126792, 2022). "Interestingly, SPHK1, with known oncogenic characteristics was the only gene upregulated with > 2.0-fold change and tumour suppressors namely AKR1B1 and KMT2C were down regulated in PDAC-CP." (PMID 35854233, 2022). "One study showed that Cinobufotalin was one of the active components of LS, and it could inhibit the expression of SPHK1 in A549 cells, thereby suppressing the growth of tumor cells." (PMID 36034844, 2022). "SphK, with two isoforms (SphK1 and SphK2), is a bioactive enzyme capable of converting sphingosine into S1P, which is a lipid mediator playing a major regulatory role in tumor cell growth, survival, invasion, angiogenesis and therapeutic resistance." (PMID 35184376, 2022). "Further evaluation of SPHK1 levels in paraffin-embedded, archived clinical tumor specimens of NSCLC cases, using IHC analysis with an antibody against human SPHK1, revealed significantly elevated SPHK1 levels in NSCLC cases compared to the matched adjacent tissue." (PMID 36361531, 2022). "Preclinical studies have found that elevated expression of SPHK1 could result in tumor migration, invasiveness, and angiogenesis by several mechanisms, such as the SPHK1/miR-144-3p/FN1 and SPHK1/p-PAK axes." (PMID 36050478, 2022). "Moreover, in HNSCC, Zhao and colleagues reported that miR124 acts as a tumor suppressor by inhibiting the expression of sphingosine kinase 1 and its downstream signaling." (PMID 36358691, 2022). "SphK1 mRNA/protein expression in tumor tissues was unchanged with SKI-V administration." (PMID 35115496, 2022). "Next, we hypothesized that SPHK1‐packaged EVs can increase the concentration of S1P in the tumor microenvironment, further inducing immune suppression." (PMID 35289120, 2022). "Taken together, our findings exhibit the vital role of the SPHK1/S1PR3/PBX1 axis in regulating the cell cycle of NSCLC, and targeting SPHK1 may develop a therapeutic effect in tumor treatment." (PMID 36361531, 2022).
tumor (continued). "In addition, study of in situ tumor transplantation model in nude mice showed that the suppression of SphK1 inhibited the growth of colonic orthotopic implantation tumors and the expression of paxillin, p‐paxillin, LC3 in the tumor." (PMID 34268882, 2021). "They reported that SphK1 knockdown could remarkably suppress tumor cell proliferation, block cell cycle, induce apoptosis, and inhibit their invasiveness." (PMID 35201458, 2021). "It has been shown that miR-515-5p also mediates its tumor suppressor roles via targeting SphK1." (PMID 35201458, 2021). "Moreover, high SPHK1 expression is significantly related to tissue location, clinical stage, and tumor status." (PMID 33506044, 2021). "Furthermore, miR-128 overexpression in a tumor mice model reduces tumor weight and tumor growth rate and suppresses SphK1." (PMID 35201458, 2021). "Potential developments in this field to alleviate this limitation might include some chemical modifications designed to increase the specificity for SPHK1 or targeting an upregulated sphingolipid in a specific tumor." (PMID 34737957, 2021). "SphK1 overexpression increased tumor burden in a mouse xenograft model." (PMID 34069611, 2021). "SPHK1 regulates tumor cell apoptosis and promotes NSCLC development." (PMID 34616731, 2021). "SphK1 activity was inhibited by I-BET726 (50 nm) in the primary skin SCC cells (“C1/C2”) as well." (PMID 32371868, 2020). "ERBB2-induced gene expression profiles as determined by microarray analysis included cytokeratin 20 (Krt20), Sry-related HMG box gene-17 (Sox17), amphiregulin (Areg), MUC1, and sphingosine kinase 1 (Sphk1) among the genes strongly correlated with tumor growth and metastases of CC cells." (PMID 32708604, 2020). "In addition, a previous study demonstrated immunopositive staining of SphK-1 in the alveolar cells, foamy macrophages, and ECs of blood vessels in both normal and tumor tissues from the lung." (PMID 32185202, 2020). "Moreover, SphK1 and S1P encourage tumor growth and angiogenesis, metastasis and apoptotic resistance." (PMID 31809267, 2019). "Thus, alterations in SPHK1 expression potentially promote tumor development and progression of FMTs, and SPHK1 should be further investigated as a potential biomarker to predict clinical FMT patient outcome." (PMID 31101115, 2019). "In addition to a reduction in the number of tumors, the maximum size of tumor was decreased by 60% in SphK1−/− mice compared to WT at 34 weeks post-DEN injection." (PMID 29643998, 2018). "Furthermore, long-term survival assays show that SphK1−/− tumor cells formed fewer and smaller colonies in soft agar than WT tumor cells, indicating that SphK1−/− tumor cells have less growth potential than WT tumor cells." (PMID 29643998, 2018). "The knockdown of SphK1/S1PR3 effectively reduced tumor growth and lung metastasis in vivo." (PMID 29385066, 2018). "Primary SphK1−/− tumor cells showed much slower growth than primary WT tumor cells." (PMID 29643998, 2018). "In this pathway, miR-124 inhibits the SphK1 activity directly, which moves the ceramide-sphingosine-S1P rheostat toward accumulation of ceramide in tumor cells, and consequently, activates the pro-apoptotic members and inhibits the anti-apoptotic members of the Bcl-2 family." (PMID 28212569, 2017). "All of these results exhibited that restored miR-124 expression could lead to ceramide accumulation in tumor cells via inhibiting SphK1 expression." (PMID 28212569, 2017). "However, the biological functions of Sphk2 are largely different from Sphk1: Sphk1 acts as an oncogene and Sphk2 exerts tumor suppressive roles in colorectal carcinogenesis and progression." (PMID 28991193, 2017). "Tumor multiplicity (1.00 vs. 1.64 per colon, respectively, P < 0.05) and tumor volume (14.82 mm3 vs. 29.10 mm3, P < 0.05) were both significantly reduced in SphK1 KO mice compared to wild-type mice." (PMID 28583134, 2017).
tumor (continued). "Together, these results show that icaritin inhibits SphK1 activity and HepG2 tumor growth in vivo." (PMID 28206952, 2017). "We were not able to identify any association between IGF1R or SphK1 and tumor grade; however, p-IGF1R was inversely correlated to tumor grade in our analysis (p = 0.004)." (PMID 29207959, 2017). "Our data indicate that, in MM, FTY720 significantly inhibited the enzymatic activity of the oncogene SphK1 and reactivated the tumor suppressor activity of PP2A, suggesting that FTY720 anti-tumor activity may be exerted via modulation of these effectors." (PMID 28298211, 2017). "Accordingly, the proliferation rate and the cell viability were significantly inhibited in SphK1-silenced A498 and 786-O cells, demonstrating that SphK1 activity promotes a survival advantage in accord with the notion that HIF-2α contributes to tumor cell survival." (PMID 26974204, 2016). "Whereas targeting of TGF-β signaling is therapeutically challenging, inhibiting a downstream effector SPHK1 could be a promising therapeutic strategy aimed at the tumor stroma." (PMID 26716409, 2016). "In conclusion, PRSS8 acts as a tumor suppressor by inhibiting Sphk1/S1P/Stat3/Akt signaling pathway, and could be used as a biomarker to monitor colorectal carcinogenesis and predict outcomes." (PMID 27050145, 2016). "However, we are the first to demonstrate that stromal SPHK1 expression is required for the myofibroblastic conversion and tumor-promoting effects of CAFs." (PMID 26716409, 2016). "A majority of studies on SPHK1 have focused on its role in tumor cells." (PMID 26716409, 2016). "We found that HULC accelerated the tumor growth derived from HepG2 (or Huh7) cells in nude mice, but the treatment with si-SPHK1-1 could markedly block the tumor growth." (PMID 26540633, 2016). "Univariate log-rank analysis identified the following factors as adverse influences on OS: presence of symptoms, decreased albumin levels, elevated alkaline phosphatase and CEA levels, tumor size >5 cm, positive surgical margin and lymph node status, and SPHK1 immunostaining." (PMID 26090720, 2015). "SPHK1 transcript was significantly over-expressed in tumor tissues." (PMID 26090720, 2015). "A number of preclinical studies have shown that pharmacological inhibition of SphK1 could be efficacious in decreasing tumor size or sensitize to chemo- or radiotherapy." (PMID 25915662, 2015). "In addition, we showed that FTY720 significantly decreased the intracellular enzymatic activity of SPHK1 and the expression level of MMP-2 and VEGF-A, both of which are closely linked to tumor invasion, metastasis, and angiogenesis." (PMID 26311741, 2015). "It remains to be determined whether this increase in circulating S1P is derived directly from tumour SPHK1 activity, or from host cells." (PMID 24970218, 2014). "Mounting evidence has shown that SphK1 plays an important role in regulating tumor cell apoptosis." (PMID 25109605, 2014). "Mice receiving radiation and the SphK1 siRNA-graft had the greatest reduction in tumor volume (94%); mice receiving the SphK1 siRNA-graft had the next greatest reduction (67%); those mice receiving radiation (and the GFP-graft) had the smallest tumor volume reduction (17%)." (PMID 24970177, 2013). "In addition, IHC showed that 50% of tumor cells from SphK1 KO mice stained positive for cleaved caspase-3 (indicative of apoptosis), versus 24% of tumor cells from WT mice." (PMID 24970177, 2013). "SphK1 is differentially regulated in HNSCC, and it is possible that perturbations in SphK1 activity may affect other sphingolipids, which could exacerbate or reduce tumor progression." (PMID 24970177, 2013). "In addition, microarray analysis of human HNSCC tumor samples showed that SphK1 expression correlates with genes downstream of the EGFR pathway in ESCC (i.e., amphiregulin, integrinα5, epiregulin)." (PMID 24970177, 2013). "S1P levels and lymphangiogenesis in tumor are lowered by treatment with SphK1 inhibitor." (PMID 24286034, 2013).
tumor (continued). "Sphingosine kinase 1 expression was successfully assessed in all tumours analysed." (PMID 22460268, 2012). "In 23 cases (76%), SPHK1 expression appeared to be upregulated in the tumors when compared to the companion normal tissue with the following immunostaining scores: normal: 0.93 ± 0.173; tumor: 2.06 ± 0.46, P < 0.01." (PMID 21936950, 2011). "Expression of sphingosine kinase-1 (SphK-1) correlates with a poor survival rate of tumor patients." (PMID 20508814, 2010). "Also, there is a positive correlation between SPHK1 expression and tumor-grade or -stage." (PMID 39284838, 2024). "However, the exact mechanism of SPHK1 drives autophagy to promote tumor progression remains unclear." (PMID 38135696, 2024). "Therefore, SphK1 inhibitors have been used to suppress tumor growth." (PMID 36839802, 2023). "In order to investigate whether, besides affecting the migration properties of microglia and macrophages, S1P also acts as a stimulus to alter their activation status, we set up a co-culture system with murine primary microglia cells and tumor cells either overexpressing or downregulating SPHK1." (PMID 36672428, 2023). "Thus, we sought to determine if EVs release SPHK1 into the tumor microenvironment." (PMID 35289120, 2022). "In addition, we confirmed the prevalence of CNV alterations in ARGs in COAD patients, and CNVs seem associated with higher expression of ARGs in tumor tissues, such as NF1, COL4A2, C1GALT1, SPHK1, RUNX1, implying a potential regulatory role of CNVs on the expression of ARGs." (PMID 36505481, 2022). "To further determine how SPHK1 upregulates PD‐L1 and how it affects tumor growth in vivo, we ectopically expressed (EE) SPHK1 in HeyA8 cells and orthotopically injected those cells or control cells into the ovarian bursa of nude mice and monitored tumor growth." (PMID 35289120, 2022). "In our studies, targeting the SPHK1/S1PR3 axis with inhibitors reduced the expression of SPHK1 and S1PR3 and the biosynthesis of S1P (data now shown), significantly suppressed TSC2-deficient cells metastasis and prolonged the survival of mice carrying xenograft tumor." (PMID 36543771, 2022). "The expression levels of SphK1 and paxillin were significantly relevant to tumor pathological stage, presence of lymphatic metastasis, and development of distant metastasis, moreover, the expression of paxillin is closely correlated with the expression of SphK1 in CRC tissues." (PMID 34268882, 2021). "The two isoforms of SphK, SphK1, and SphK2, catalyse the conversion of the membrane phospholipid sphingosine to the bioactive lipid S1P, an oncogenic mediator which drives a number of vital processes in tumor cells, including cell growth, survival, migration, invasion, and angiogenesis." (PMID 34768523, 2021). "Many studies have suggested that the SphK1/S1P axis could play a role in the promotion of several types of tumors, based on the overexpression of SphK1 in tumor cell lines and in patient samples, and sometimes, on the measured increased S1P levels in tumors and/or in patient blood." (PMID 33450869, 2021). "Hence, targeting SPHK1-S1P-STAT1 could trigger multifaceted anti-tumor responses and may be a promising approach warranting further development." (PMID 32260399, 2020). "Second, it could restrain SPHK1 translocation from the cytoplasm to the plasma membrane and further pyroptosis, which not only drive M2 macrophages death but also facilitate tumor microenvironment inflammation as well as the further release of sphingosine from damaged macrophages." (PMID 33123153, 2020). "Thus, inhibiting the enzymatic activity of SPHK1 might contribute greatly to TAMs pyroptosis to promote anti-tumor progression." (PMID 33123153, 2020). "Next, we investigated whether SPHK1 reduces the tumor suppressive function of STAT1." (PMID 32260399, 2020). "Similarly, SPHK1 mRNA exhibited higher expression in tumor cells and tissues than in normal cells." (PMID 31133022, 2019).
tumor (continued). "Indeed, we found massive senescence in cultured SphK1−/− tumor cells as well as MEF." (PMID 29643998, 2018). "Therefore, we analyzed whether miR-124-mediated inhibition of SphK1 expression could shift the ceramide-S1P balance toward ceramide in culture cells and tumor xenografts." (PMID 28212569, 2017). "Interestingly, we showed that the expression of SphK1 decreases with tumor grades." (PMID 28672103, 2017). "SPHK1 has an important role in activation of cell proliferation, inflammatory response, migration and dysfunction in apoptosis, and its expression in tumor cells can lead to tumor growth, drug resistant, oncogenic transformation, neovascularization of tumors, and metastatic spread." (PMID 29531546, 2017). "Importantly, inhibiting SphK1 significantly decreased S1P levels in serum and tumors in these mice, and both angiogenesis and lymphangiogenesis were suppressed, not only around the primary tumor but also in lymph nodes that were distant from the tumor." (PMID 28912626, 2017). "To investigate the role of HULC in tumor angiogenesis, we screened the expression of several tumor angiogenesis-associated factors, such as VEGF, SPHK2, transforming growth factor-beta receptor 2 (TGF-βR2), monocyte chemoattractant protein 1 (MCP1) and SPHK1, in HULC over-expressed HepG2 cells." (PMID 26540633, 2016). "Similarly, both expression and activity of SphK1 were increased in sunitinib-resistant renal cell lines, and a gene-expression analysis of different tumor cell lines resistant to oxaliplatin, cisplatin, and docetaxel identified that drug resistance was related to SphK1 expression." (PMID 27800303, 2016). "Also, the increased S1P content detected in human glioblastoma tissue was associated with SphK1 expression but inversely correlated with SPP2 expression, suggesting that the shift of the S1P rheostat may play a role in the development of this tumor." (PMID 27800303, 2016). "Importantly, although many SphK1 inhibitors were shown to decrease angiogenesis, tumor growth, and proliferation, only one Phase I clinical trial with Safingol (SphK1 inhibitor) in combination with Cisplatin has been completed (NCT00084812) and indicated absence of toxicity." (PMID 27800303, 2016). "Interestingly, microRNAs (miR), which may act as oncogenes or tumor suppressors, also regulate the expression of SphK1." (PMID 27800303, 2016). "Moreover, recent studies showed that SphK1 may be involved in resistance to both chemotherapeutics and targeted agents, suggesting that inhibitors of SphK1 in combination with chemotherapeutic treatments can synergistically act to induce tumor cell death." (PMID 26673009, 2016). "SPHK1 IHC Quick-score = intensity x proportion: intensity scored as 0 = negative, 1 = weak, 2 = moderate and 3 = strong SPHK1 staining in tumour cells; positive proportion scored as 0 = 0 %, 1 = 1-10 %, 2 = 11-50 %, 3 = 51-70 %, and 4 = > 70 % tumour cells positive for SPHK1 staining." (PMID 26493335, 2015). "In addition there may be a change in the SPHK1 expression from the primary tumour that was resected and the recurrent disease at a later date when palliative chemotherapy might be administered." (PMID 26493335, 2015). "This RhoA activation in lipin-1-depleted cells could be related to the increased concentration of PA which can activate the sphingosine kinase-1 to produce sphingosine-1-phosphate, a lipid mediator able to enhance RhoA activity, and to inhibit migration of various tumor cells including PC-3." (PMID 25834103, 2015). "Thus, the anti-tumour effects of SPHK1/2 inhibitors such as dimethylsphingosine (which is known to inhibit PKC) and SKI-II may relate to off-target mechanisms." (PMID 24970218, 2014). "Hence, it is expected that S1P1 induction in concert with sphingosine kinase 1 and S1P production in tumor microenvironments may contribute to the progression of HCC to more aggressive phenotype." (PMID 24798342, 2014).